DEDD2 (death effector domain containing 2)
Description:
May play a critical role in death receptor-induced apoptosis and may target CASP8 and CASP10 to the nucleus. May regulate degradation of intermediate filaments during apoptosis. May play a role in the general transcription machinery in the nucleus and might be an important regulator of the activity of GTF3C3.
Synonyms: FLAME3; FLAME-3
Tractability: PROTAC: ubiquitination databases record sites on it.
Gene: Protein-coding gene on chromosome 19 (42,198,593 to 42,220,140, reverse strand). Ensembl gene ENSG00000160570.
Subcellular location: Nucleus, nucleolus
Subcellular location (Human Protein Atlas): Nucleoplasm
Pathways (Reactome):
Cellular responses to stimuli: Attenuation phase; HSF1 activation; HSF1-dependent transactivation; Regulation of HSF1-mediated heat shock response
Gene Ontology:
Molecular function: protein binding; DNA binding; signaling receptor complex adaptor activity
Biological process: apoptotic nuclear changes; extrinsic apoptotic signaling pathway via death domain receptors; positive regulation of extrinsic apoptotic signaling pathway; cellular homeostasis; intracellular signal transduction; negative regulation of DNA-templated transcription; RNA processing; rRNA catabolic process; apoptotic process; regulation of apoptotic process
Cellular component: nucleolus
Genetic constraint (gnomAD): Loss-of-function variants: 18 observed, 23.83 expected, observed/expected ratio (o/e) 0.76, 90% interval 0.52 to 1.12. The upper end of that interval is the gene's LOEUF score, 1.12, which puts it in group 4 of 6, group 1 being the genes least tolerant of losing a copy. Missense variants: 411 observed, 440.68 expected, observed/expected ratio (o/e) 0.93, 90% interval 0.86 to 1.01. Synonymous variants: 211 observed, 191.23 expected, observed/expected ratio (o/e) 1.1, 90% interval 0.99 to 1.24.
Homologues: Orthologues: macaque DEDD2 (99% identical), rabbit DEDD2 (97% identical), dog DEDD2 (96% identical), guinea pig DEDD2 (95% identical), pig DEDD2 (95% identical), mouse Dedd2 (93% identical), chimpanzee DEDD2 (92% identical), rat Dedd2 (85% identical), tropical clawed frog dedd2 (50% identical), zebrafish dedd1 (49% identical). Paralogues in human: DEDD (41% identical).
Diseases named in the same sentence as DEDD2 in open-access papers:
DEDD2 is named in the same sentence as 8 diseases in open-access papers, as found by Europe PMC text mining. Sharing a sentence is not in itself a finding about the gene and the disease. The quoted sentences say what the papers report.
colon cancer (1 paper, 2022). "Our findings indicated that DEDD2, GTF2H5, SNRPA1, BICD1, CELF1, and CLK3 were prognostic risk factors for colon cancer, while ADAD1, CMTR1, HNRNPUL1, FTSJ3, WDR43, THUMPD3, SNRPF were prognostic protective factors." (PMID 36212157, 2022).
pancreatic cancer (1 paper, 2018). "We also showed that the genes encoding proapoptotic proteins, namely DEDD2, DAPK3, and NLRP1, were overexpressed in pancreatic cancer cell lines treated with AbE." (PMID 30514293, 2018).
cancer (2 papers, 2013 to 2018). A tumor composed of atypical neoplastic, often pleomorphic cells that invade other tissues. "However, the functional roles of BAG3 and DEDD2 in cancer cell response to HSP90 inhibition are not explored." (PMID 23615731, 2013).
infection (1 paper, 2017). The state of being infected such as from the introduction of a foreign agent such as serum, vaccine, antigenic substance or organism. "Finally, several pro-apoptotic genes, including Bcl3, Bcl10, Malt1 and Dedd2, were up-regulated in response to muriform cells infection whereas Bcl2l12, coding to anti-apoptotic factor, was down-regulated, suggesting that infection of macrophages with muriform cells could induce apoptosis." (PMID 28355277, 2017).
tumor (1 paper, 2021). "The heatmap showed that 12 tumor suppressors formed into two clusters: cluster 1 contains seven downregulated tumor suppressors including PTEN, PSME1, DNAJB1, HSPH1, DEDD2, PAK1IP1, and MIR1244-3; and cluster 2 contains five upregulated tumor suppressors (OSGIN1, IFI27L1, MTCH2, NKD2, and IBTK)." (PMID 34571936, 2021).
DEDD2 also shares sentences with these, for which no sentence is quoted: hookworm infection (1 paper); Obesity (1); periodontitis (1).